SRC (SRC proto-oncogene, non-receptor tyrosine kinase)
Diseases named in the same sentence as SRC in open-access papers (continued):
Sharing a sentence is not in itself a finding about the gene and the disease.
cancer (continued). "We focused on SRC, given its known roles in cancer progression and metastasis (33, –, 42) and because it is frequently up-regulated or activated in human cancers (39, 42, –, 46)." (PMID 30559289, 2019). "As an attempt to enhance the clinical benefit of SRC inhibitors, various combinational regimens with other anti-cancer agents have been designed and have shown promising results." (PMID 31731442, 2019). "For example, the increased expression of αvβ3 integrin and SRC activation is seen in cancer stem cell like phenotype, resistance to anoikis and increased metastasis in breast and lung cancers." (PMID 31781558, 2019). "Accordingly, patients carrying SRC-positive tumors showed a significantly higher rate of cancer-related deaths (p = 0.001)." (PMID 31731442, 2019). "Consistent with studies in nontransformed cells, we found that GIT1 is phosphorylated in an SRC-dependent manner in cancer cells." (PMID 30559289, 2019). "For instance, SLAP overexpression reduces SRC cancer activities, while its inactivation potentiates this malignant process." (PMID 31091767, 2019). "Instead, the elevated SRC activity observed in many human cancers is the result of aberrant signaling by other pathways." (PMID 30559289, 2019). "Like YAP and TAZ, SRC is a known driver of cancer progression and metastasis (33, –, 36, 39, –, 41, 58)." (PMID 30559289, 2019). "Numerous oncogenic pathways activate SRC, and many signals from the tissue microenvironment that are altered in cancer can drive SRC activation (76, –, 79)." (PMID 30559289, 2019). "In colon cancer, LOX enzymatic activity was shown to drive cancer cells proliferation and invasion through SRC activation mediated by β3 and β4 integrins." (PMID 31130685, 2019). "Aberrant SRC expression and activation is frequent in a wide variety of cancers and has been identified as a central node in numerous oncogenic pathways, thereby playing critical roles in tumor formation, progression, and dissemination." (PMID 31731442, 2019). "Paradoxically, not only SRC inhibition, but also hyper-stimulation can be exploited to selectively induce cancer cell death and in vivo tumor growth inhibition." (PMID 30382692, 2018). "A high-throughput screen identified a small molecule (MCB-613), which over-activates SRC transcriptional programs, leading to excessive cellular stress in cancer cells that highly rely on proper SRC functioning." (PMID 30382692, 2018). "EGFR promotes cell migration and invasion signaling in cancer cells through activation of cell adhesion, SRC, AKT, MAPK and endosomal signaling pathways." (PMID 29455656, 2018). "We showed that cell surface presentation of fibroblasts-derived FGF-2 to cancer cells, leads to integrin αvβ5-dependent and SRC-mediated adhesion of cancer cells to fibroblasts, and contact-dependent tumor cell elongation, migration and invasion." (PMID 30065926, 2018). "Dasatinib reduced SRC phosphorylation in cancer cells and or Erdafitinib inhibited FGF-2 production in fibroblasts." (PMID 30065926, 2018). "The product of the human SRC gene, c-Src, is found to be over-expressed and highly activated in a wide variety of human cancers." (PMID 29455673, 2018). "This cancer-promoting activity correlates with the Warburg effect through the activation of the SRC/ERK/c-MYC/PFKFB2 pathway." (PMID 29523788, 2018). "Mechanistically, the SLIT2/ROBO1 axis exerted cancer-promoting effects on OS via activation of the SRC/ERK/c-MYC/PFKFB2 pathway." (PMID 29523788, 2018). "Our GSEA analysis also indicates that GGT is significantly correlated with EMT, KRAS, SRC and PKCA pathways, which are closely associated with cancer metastasis and proliferation." (PMID 28404903, 2017). "Auto-phosphorylation of FAK and activation of SRC is regulated by integrin clustering which dependents on Galectin-3 on the surface of cancer cells." (PMID 28701735, 2017).
cancer (continued). "SRC is a proto-oncogene that is aberrantly activated in most types of cancer, which is consistent with our results showing that SRC is significantly increased in both cell types." (PMID 28640862, 2017). "Targeting of the RAF/MEK/ERK, PI3K/PTEN/AKT/mTORC1, SRC or other signaling pathways has shown promise in anti-cancer therapy." (PMID 29100331, 2017). "This also explains well the ability of EPHB6 to protect cancer cells from shRNA-induced silencing of SRC or src knockout observed in our work." (PMID 27418135, 2016). "SRC has been shown, as it has with many other cancers, to be upregulated in PCa, with a large resource of research available." (PMID 27685442, 2016). "Despite playing a central role in multiple tumorigenic signaling networks of the SRC/FAK pathway, SRC itself is rarely mutated in cancers." (PMID 27438149, 2016). "In contrast, fibroblasts with silenced SRC expression were still able to induce cancer cell elongation." (PMID 25973543, 2015). "SRC inhibition also prevented scattering and invasion of cancer cells in the 2D and 3D spheroid models." (PMID 25973543, 2015). "Basal levels of membrane-associated phospho-SRC were observed in SW620 and HT29 cultured alone and more frequently in elongated cancer cells, in particular at sites of contact with fibroblasts." (PMID 25973543, 2015). "To circumvent these limitations we silenced SRC through lentiviral-mediated expression of SRC-specific shRNA in cancer cells or in fibroblasts." (PMID 25973543, 2015). "The active SRC pathway has also been documented in upwards of 50% of tumors derived from several cancers, including NSCLC." (PMID 26358373, 2015). "Thirdly, we identify FGFR, SRC and αvβ5 as the molecules mediating cancer cell adhesion on fibroblasts, migration and invasion." (PMID 25973543, 2015). "From these experiments we concluded that fibroblast-induced cancer cell elongation, motility and invasion depend on SRC activation in cancer cells." (PMID 25973543, 2015). "Nuclear phospho-SRC was observed in cancer cells in contact with fibroblasts and in fibroblasts themselves." (PMID 25973543, 2015). "We found that neoplastic MDSCs differentially expressed a core of kinases which controlled lineage-specific (PI3K-AKT and SRC kinases) and cancer-induced (ERK and PKC kinases) protein interaction networks (interactomes)." (PMID 26320174, 2015). "In the case of the human endometrium, elevation of SRC expression levels has been correlated with endometrial hyperplasia and cancer and with endometrial samples biopsied from patient groups predisposed to endometrial tumorigenesis." (PMID 24905738, 2014). "As a potent oncogene, SRC regulates the proliferation and motility of cancer cells by affecting the FAK, EGFR, and Ras/ERK signaling pathways." (PMID 25140799, 2014). "The cellular tyrosine kinase, SRC, is frequently overexpressed or aberrantly activated in a range of cancers." (PMID 25140799, 2014). "SRC and the Src family of proteins have been extensively characterized to have important roles in the proliferative and invasive abilities in many cancers including glioblastoma." (PMID 24465609, 2014). "SRC protein overexpression was found in 80 cases of malignant tumors, representing 10 tumor types, including breast, cerebrum, colon, esophagus, kidney, liver, lung, prostate, stomach and uterus." (PMID 24130815, 2013). "High levels of endogenous SRC are thought to promote invadopodia that form spontaneously in invasive cancer cells or following activation of growth factor signaling pathways." (PMID 22973180, 2012). "The positive correlation between FBLIM1 (filamin binding LIM protein 1) and SRC (v-srcsarcoma viral oncogene homolog [avian]) overexpression resulted in anoikis resistance contributing to tumorigenicity of established carcinoma cells." (PMID 22984562, 2012). "Our analysis showed that AATF, LGALS3, and SRC are up regulated in 8/13 of cancer models, and CDC2L2, E2F6, LGALS9, PDCD8, RELB, TRADD, and TRAF2 in 7/13." (PMID 19402918, 2009).
cancer (continued). "Treatment with SRC inhibitors and autophagy inducers exhibited synergism invitro, in ovo and in patient-derived tumor organoids with BAP1 loss, paving the way for treating BAP1-deficient cancers with autophagy inducers and kinase inhibitors." (PMID 40754831, 2025). "SRC is a well-known oncogene that plays a central role in various cancer signaling pathways." (PMID 41220926, 2025). "This indicated that ERBB2 downstream pathway in canine iUC relied on the PI3K/AKT pathway, although ERBB2 could regulate multiple downstream pathways, such as MAPK and SRC, in human cancers." (PMID 40966256, 2025). "Integrins associate with different intracellular signaling pathways, including the small MAPK, GTPases, RhoA and Rac, the Hippo signaling pathway, and focal adhesion kinase (FAK) and SRC (a protein kinase that plays a role in development and progression of several cancers)." (PMID 40305177, 2025). "Since ALK (EML4-ALK) and SRC play a role in other cancers, this approach may have broader relevance." (PMID 41154443, 2025). "We determined that EPHB2 has significant interactions with several key proteins, including L1CAM, ABL2, KDM4A, BTF3, and SRC, suggesting that it may form a functional network critical to cancer progression." (PMID 41322437, 2025). "Genes NOG, TGFB1, VIRMA, and SRC were over-expressed in cancer." (PMID 40724805, 2025). "Our findings suggest SRC as a prognostic biomarker in pan-cancer." (PMID 39859167, 2025). "MAP1LC3A and SRC showed notable heterozygous amplifications in cancers like BRCA and LIHC." (PMID 39859167, 2025). "The current network pharmacology-based analysis of A. laxiflora suggested that compounds (quercetin, 3-acetylursolic acid, and 3-acetyloleanolic acid) in this plant can influence key cancer-associated targets EGFR, AKT1, SRC, and MAPK1 through the PI3K-Akt, MAPK, Ras, and Rap1 signaling pathways." (PMID 40283942, 2025). "On the other hand, SRC displayed a potential inhibitory effect on the cell cycle (16%), hormone AR (16%), hormone ER (hormone estrogen receptor; 16%) and apoptosis (12%) pathways in pan-cancer." (PMID 39859167, 2025). "Inhibition of AXL and SRC led to increased levels of pro-apoptotic proteins in cancer cells." (PMID 39941857, 2025). "In cancer cells, SRC is often aberrantly activated, promoting tumor growth and metastasis." (PMID 38769413, 2024). "Targeting SRC overcomes G12Ci resistance in KRAS-G12C mutant cancers." (PMID 39661665, 2024). "Some representative biological events including ITGB1 activation and concomitant activation of several signaling molecules such as FAK and SRC were recognized as hallmarks of FA formation and maturation, and have also been demonstrated to be particularly important in cancer metastasis." (PMID 38326908, 2024). "Furthermore, HER3 can activate other signaling pathways including janus kinase (JAK) and proto-oncogene c-Src (SRC) involved in cancer proliferation." (PMID 38951909, 2024). "SRC is a proto-oncogene tyrosine kinase and is expressed at elevated levels in numerous cancers." (PMID 37166992, 2023). "Although many details are still unknown about the role of c-SRC, its role in the development and progression of different types of cancer is well established." (PMID 37759706, 2023). "All these data confirmed that SRC activation could indeed enhance the cancer stemness in TNBC cells." (PMID 36633714, 2023). "We further identified the YAP1-KLF5 oncogenic module was responsible for SRC-induced cancer stemness in TNBC cells, targeting YAP1-KLF5 module thus may represent a more precise therapeutic strategy for treating SRC activation-associated TNBC." (PMID 36633714, 2023). "The role of SRC in cancers has been well-established; besides, up-regulated SRC kinase in the microenvironment could promote inflammation." (PMID 36672292, 2023). "The SRC protein is crucial in chronic inflammation and cancer development." (PMID 37993790, 2023).
cancer (continued). "Disruption of YAP1-KLF5 attenuated SRC activation-induced cancer stemness and metastasis." (PMID 36633714, 2023). "SRC facilitates the invasion and metastasis of cancer cells by accelerating their function." (PMID 37439249, 2023). "Further investigation into the transcriptional mechanisms of SRC might provide promising targets for anti-cancer drugs that prevent tumour invasion and metastasis." (PMID 37439249, 2023). "In addition, SRC-dependent YAP1 activation has been demonstrated to be critical for the establishment and maintenance of cancer-associated fibroblasts." (PMID 36633714, 2023). "There is growing evidence that RT-induced K-RAS/ERK signaling activation elevates CD44 expression through downregulation of miR-202 and miR-185 expression, promoting SRC activation to drive cancer stemness and EMT as a pivotal mechanism to mesenchymal transition in GBM cells." (PMID 37637066, 2023). "Therefore, further studies on the relationship between TGF-β signalling and SRC should be conducted to gain a deeper understanding of cancer progression." (PMID 37439249, 2023). "Therefore, SRC-3f/f:Foxp3Cre-ERT2/+ and SRC-3f/f female mice used in all subsequent cancer studies have a genetic background of C57BL/6J." (PMID 37253006, 2023). "To determine whether the EMT regulatory signaling pathway is dependent on ABCA1 expression, we identified the most aberrantly activated pathways, including the EGFR, SRC, and ERK pathways, which are associated with ABCA1 in various carcinomas." (PMID 36672209, 2023). "SRC, a proto-oncogene complex protein kinase, promotes the development of cancer in many respects." (PMID 36060002, 2022). "We propose that phosphorylated ICAM-1 as an adapter protein may modulate cancer malignancy by further promoting the activity of SRC on the c-MET-SRC axis." (PMID 35487888, 2022). "Based on the Connectivity MAP predictions, we tested whether saracatinib, a known SRC inhibitor previously tested in human cancer, is able to modulate IPF-ABC phenotype." (PMID 36163190, 2022). "We also examined SRC regulation of autophagy in cancer cell survival and drug resistance." (PMID 35647611, 2022). "Similarly, the seed genes SRC and VDR in two functional modules identified in the PPI network were also closely associated with cancer progression." (PMID 35273218, 2022). "When combined with dasatinib in MCF10A-WT and CDH1−/− cells, MK2206 exhibited synergy, indicating that the simultaneous targeting of SRC, DDR2 and AKT may be effective in specifically targeting E-cadherin-deficient cancer cells." (PMID 35406381, 2022). "Notably, exploration of drug combinations of MEK and SRC inhibitors have been carried out in vitro using various types of cancer cell lines and to a less degree in vivo using mouse models, where enhanced anti-cancer effects have been reported." (PMID 35272617, 2022). "Mitochondrial SRC is a crucial aspect of mitochondrial function, as it increases resistance to stress and better maintenance of cellular functions when the energy demand increases, as in cancer cells." (PMID 36497197, 2022). "As SRC inhibitors perform poorly as single anti‐cancer agents in most cancers tested (for example), we next sought to identify potential resistance mechanisms that rely upon SRC that could be targeted with drug combination therapy using AZD0424." (PMID 34856074, 2022). "Since PTK6 and SRC target many of the same substrates and PTK6 can promote SRC activation, drugs that target both kinases may have greater efficacy than targeting either kinase alone in cancer therapy." (PMID 36228719, 2022). "Interestingly, the ESR1/ESR2 ratio was characterized by a strong, negative correlation with ESR2/PELP1 ratio in OCP, and moderately strong with ESR2/SRC ratio in both benign changes of ovary and cancer affected tissue." (PMID 34207568, 2021). "In addition, SRC proto-oncogene was related to the processes of proliferation and survival of cancer cells." (PMID 34335688, 2021).
cancer (continued). "The activation of SRC in cancer predicts poor clinical results." (PMID 34307888, 2021). "Besides, we tested the clinical relevance of baseline SRC protein and mRNA expression in two independent confirmatory cohorts (n = 566) and the prognostic value in pan-cancers." (PMID 33830879, 2021). "Evidence that SRC kinase directly governs cancer EV release may reinforce the testing of SRC inhibitors in the clinic." (PMID 34532864, 2021). "A previous study revealed that activation of SRC can protect cancer cells from ferroptosis by suppressing the expression of ACSL4, an enzyme that enriches membranes with PUFAs and is required for ferroptosis, revealing the inhibitory role of SRC in ferroptosis." (PMID 34764976, 2021). "Elevated SRC protein or kinase activity has been reported in many human cancers." (PMID 34862372, 2021). "Moreover, oncoproteins of HPV and EBV can lead to the development and progression of cancer via commonly linked signaling pathways including WNT/β-catenin, JAK/STAT/SRC, PI3k/Akt/mTOR, and/or RAS/MEK/ERK." (PMID 34360884, 2021). "Interestingly, TMPRSS2 positively correlated with SRC in the pancreatic tissues in mixed healthy and cancer datasets." (PMID 33796097, 2021). "Thus, this novel and dramatic synthetic lethal effect conferred by mIDH and SRC will be a potential treatment protocol for relevant cancers." (PMID 34425876, 2021). "CD44 and its multiple splice variants are involved in a variety of cancer mechanisms, including angiogenesis via the ERM-VEGFR axis, cell proliferation via the ERM-VEGFR-MAPK axis, metabolic shift in cancer cells via the SRC-AKT axis, and cancer cell invasion via the HGF-MET-PI3K-AKT axis." (PMID 34570764, 2021). "Based on the established oncogenic role of SRC in general cancer development and in particular in CRC and on the described analysis results of the FCVPPv2, the identified SRCV177M variant was considered to bear pathogenic potential leading to its prioritization for functional validation." (PMID 33916261, 2021). "Furthermore, the phosphorylation levels of EGFR, ERBB2, GRB2, and SRC were significantly reduced in the PAF-AH 1B2 KD cancer cells as determined by the Luminex assay and western blot data." (PMID 34930255, 2021). "Thus, CCT3833 inhibits both CRAF and SRC in KRAS-mutant cancers and so we investigate the contribution of these two activities to the inhibition of long-term cell growth." (PMID 33130216, 2021). "In those cancer cells, LIF promoted invadopodia-associated characteristics and markers, such as tyrosine kinase substrate with five SH3 domains (TKS5), cortactin (CTTN), matrix metallopeptidase 2 (MMP2) and SRC proto-oncogene (SRC)." (PMID 34361105, 2021). "Furthermore, the data point at the interplay between Rho and RASSF1C/SRC pathways as a driver of cancer stemness and aggressiveness." (PMID 34532864, 2021). "Lamar and colleagues have reported that increased SRC activity may be the driver of high activity of YAP1/TAZ in human cancers." (PMID 34693980, 2021). "Notably, RAF and SRC are validated targets in RAS-mutant cancers, because RAF signals downstream of oncogenic KRAS, and SFKs drive cancer cell proliferation and survival." (PMID 33130216, 2021). "We found that MCL1, Cofilin1 (CFL1) and SRC mRNA were highly expressed by a wide range of these cancers, suggesting that a strategy of dual MCL-1 and SRC inhibition might be efficacious for many patients." (PMID 31735913, 2020). "In particular, tumor cells release chemokines (such as, SDF-1, MIP-1, MCP-1, MIP-2, etc.)that trigger the activation of SRC kinase in immune cells, which in turn release other cytokines (TNF-α, IL-1β, IL-6, etc.)reciprocally activating SRC in cancer cells through a positive feedback mechanism." (PMID 32545574, 2020).